PGAM2 (phosphoglycerate mutase 2)
Diseases named in the same sentence as PGAM2 in open-access papers (continued):
Sharing a sentence is not in itself a finding about the gene and the disease.
cancer (12 papers, 2015 to 2026). A tumor composed of atypical neoplastic, often pleomorphic cells that invade other tissues. "In the present study, we also found that the PGAM2-K176R mutation impaired glycolysis in P19 cells, a cancer cell line." (PMID 36589741, 2022). "PGAM2 exhibits a well-defined role in the Warburg effect, which is closely associated with cancer growth and metastatic progression." (PMID 36589741, 2022). "Similarly, the glycolytic enzymes Pkm2, Tpi1, Pgam2, and Pfkl are known to be highly expressed in various cancers, and are associated with poor prognosis." (PMID 31336728, 2019). "PGAM2 is upregulated in several cancers and can be critically increased by an alternative glycolytic pathway originating via a cancer-specific isoform of pyruvate kinase." (PMID 41294712, 2025). "Studies in cancer cells have shown that PGAM2 plays a significant role in the Warburg effect (i.e., increased glycolysis, a characteristic of cancer cells)." (PMID 36589741, 2022). "Although we previously reported that both PGAM-1 and -2 affect global glycolytic profile of cancers in vitro, in vivo glucose parameters were less affected both in the heterozygous knockout of Pgam1 and in Pgam2 transgenic mice." (PMID 33914812, 2021). "Phosphoglycerate mutase 2 (PGAM2) is a glycolytic enzyme known to be expressed in anaerobic tissues including skeletal muscle and cancers cells." (PMID 29236774, 2017). "High PGAM2 in cancer tissues was observed in 9.3% of the patients." (PMID 29362480, 2018). "In addition, PGAM2 being a glycolytic enzyme can be very useful in monitoring glycolysis as a fundamental metabolic pathway in cancer development." (PMID 29312627, 2017). "However, PGAM2 is one of few energy metabolism–related enzymes that does not undergo transcriptional regulation by heat-induced factor 1 alpha (HIF1a), which is a master regulator of energy metabolism in cancer cells under hypoxia." (PMID 36589741, 2022). "Because PGAM2 plays an important role in energy production in cancer cells, we asked whether the sumoylation site K176 is also critical for PGAM2 to mediate energy production in cancer cells." (PMID 36589741, 2022). "Thus, the SUMO site K176 is also important for PGAM2 to mediate glycolysis in cancer cells." (PMID 36589741, 2022). "Thus, direct targeting of PGAM2 transport to nucleoli might be worth considering as a part of a new anti-cancer combination therapy." (PMID 26033454, 2015). "Initial steps include analytical validation of a serum assay panel (p-cresol, S1P, 7-HOCA, DLST, MSR1, PGAM2, and ATG5) as well as known hallmarks of cancer proteins with standardized pre-analytics and central IDH and MGMT testing." (PMID 41294712, 2025).
tumor (9 papers, 2017 to 2025). "Increased oxidative stress in tumor cells stimulates PGAM2 activity which enhances glycolytic flux (the Warburg effect), enabling cells to adapt to hypoxic conditions." (PMID 29236774, 2017). "PGAM2 is a glycolytic enzyme whose upregulation is essential for tumor cell proliferation." (PMID 31277598, 2019). "Upregulated genes such as ACSS1 (log2fc =0.50), PFKFB2 (log2fc = 0.57), GCK (log2fc =0.59), and PGAM2 (log2fc =0.59) indicate potential metabolic adaptations that may support tumour growth, though their impact is less pronounced compared to the WWOX/HIF1A ratio." (PMID 41007296, 2025). "PGAM2 is highly expressed in HCC and PC, and its inhibition has been shown to reduce cell proliferation and tumor growth in HCC and mouse xenograft tumor models." (PMID 39859313, 2025). "K100 acetylation reduces PGAM2 activity, while SIRT2 deacetylates and activates PGAM2, increasing NADPH production and promoting tumour cell growth." (PMID 39778006, 2025). "Consistent with RNA-seq data, the expression of SLN, TAC1, MYH8, and PGAM2 were down-regulated, whereas SDRC7, KRT16, S100A9, IL36G, and FABP9 were up-regulated in both blood (Animal #9, #11, and #12) and skin (Animal #6, #7, and #8)-induced tumours relative to normal skin controls." (PMID 31340720, 2019).
heart disease (1 paper, 2024). "PGAM2 and NDUFA1 have been described in the context of heart disease in mice and rats, respectively, but their role in humans is unknown." (PMID 38573186, 2024).
PGAM2 also shares sentences with these, for which no sentence is quoted: infection (2 papers); melanoma (2); arachnoid cyst (1); axonal neuropathy (1); benign breast tumors (1); Brain malformations (1); demyelination (1); McArdle disease (1); metabolic myopathy (1); metabolism disorder (1); muscular disease (1); myocarditis (1); myopathy (1); neuromyotonia (1); sarcoma (1); Tarui disease (1); toxoplasmosis (1).